CLEC16A (C-type lectin domain containing 16A)
Diseases named in the same sentence as CLEC16A in open-access papers (continued):
Sharing a sentence is not in itself a finding about the gene and the disease.
osteoporosis (1 paper, 2012). A condition of reduced bone mass, with decreased cortical thickness and a decrease in the number and size of the trabeculae of cancellous bone (but normal chemical composition), resulting in increased fracture incidence. "In conclusion, variation in inflammatory genes CIITA, CLEC-16A and INFG appear to contribute to bone phenotypes in elderly women and suggest a role for low-grade inflammation and MHC class II expression for osteoporosis pathogenesis." (PMID 23133532, 2012).
spinocerebellar ataxia (1 paper, 2021). "Our results demonstrate that a whole-body, inducible knockout of Clec16a in mice results in an inflammatory neurodegenerative phenotype resembling spinocerebellar ataxia." (PMID 33927318, 2021). "Though CLEC16A has not been implicated in human spinocerebellar ataxia, other mitophagic and autophagic proteins have been identified." (PMID 33927318, 2021).
immune disorders (2 papers, 2018 to 2024). "CLEC11A is involved in bone-development regulation, while CLEC16A is associated with various immune disorders, playing a crucial role in immune development." (PMID 39199873, 2024). "By contrast, our work illustrates that decrease in CLEC16A expression via genetic Clec16a KO in mice led to disrupted/incomplete mitophagy, cell death and immune dysfunction." (PMID 30226884, 2018).
infection (2 papers, 2010 to 2022). The state of being infected such as from the introduction of a foreign agent such as serum, vaccine, antigenic substance or organism. "In addition, four T. spiralis proteins were found both 4 and 8 weeks after infection, namely hypothetical protein T01_16145 (KRY36525.1), conserved hypothetical protein (XP_003366234.1), calcium-dependent secretion activator 1 (XP_003375206.1) and protein CLEC16A (KRY38014.1)." (PMID 35271623, 2022).
neurodegenerative disease (2 papers, 2016 to 2023). A disorder of the central nervous system characterized by gradual and progressive loss of neural tissue and neurologic function. "Here we show that two mouse strains carrying independent Clec16a mutations developed neurodegenerative disease characterized by motor impairments and loss of Purkinje cells." (PMID 26987296, 2016). "The shared association of CLEC16A in these diverse inflammatory, autoimmune, and neurodegenerative diseases suggests that CLEC16A could be a critical regulator of broad biological processes involving autoimmune responses and neurodegeneration." (PMID 37175930, 2023).
neurologic diseases (2 papers, 2018 to 2023). "We provide clinical and neuroimaging data to expand the current knowledge on the contribution of CLEC16A to human neurological disease and investigate the role of CLEC16A during brain development using both in vitro and in vivo model systems." (PMID 36538041, 2023). "Likewise, a role of CLEC16A in autophagy and neurologic diseases was reported in another independent mutant mouse model of Clec16a." (PMID 30226884, 2018).
cutaneous disorder (1 paper, 2025). "Notably, TNFRSF6B and CLEC16A, a less characterized gene in AD pathogenesis, have shown consistent associations with the disease across European and Asian ancestries, enhancing their critical role as immunomodulatory agents in the cutaneous disorder." (PMID 41009683, 2025).
CLEC16A also shares sentences with these, for which no sentence is quoted: systemic lupus erythematosus (6 papers); rheumatoid arthritis (3); alopecia areata (2); Crohn disease (2); primary adrenal insufficiency (2); primary biliary cirrhosis (2); allergic rhinitis (1); Arthritis (1); atopic dermatitis (1); development (1); Insulin resistance (1); juvenile idiopathic arthritis (1); lipodystrophy (1); metabolic disease (1); neuropathies (1); psoriasis (1); ulcerative colitis (1); viral encephalitis (1).